APOE (apolipoprotein E)
Diseases named in the same sentence as APOE in open-access papers (continued):
Sharing a sentence is not in itself a finding about the gene and the disease.
atherosclerosis (continued). "The regulatory effects of miR-155 in leukocyte cells were confirmed through transplantation of miR-155 deficient bone marrow into ApoE−/− mice which resulted in halted atherosclerosis." (PMID 33391256, 2020). "Malat-1 deficiency in immune cells promotes atherosclerosis in ApoE-/- mice and is thus protective against atherosclerosis." (PMID 31947625, 2020). "It has previously been shown that systemic administration of adrenomedullin or transgenic overexpression of adrenomedullin reduces the progression of atherosclerosis in an ApoE-deficient mouse line." (PMID 33268595, 2020). "The e4 variant of the ApoE gene exhibits as a modest genetic risk factor for atherosclerosis and is the most important genetic risk factor for sporadic AD in the general population." (PMID 33121058, 2020). "In the present study, we analyzed lncRNAs and mRNAs by microarray at different time points during the atherosclerosis process in ApoE-deficient mice fed a high-fat diet under CIH or normoxia conditions." (PMID 32328084, 2020). "The apoE-deficient (apoE -/-) mouse is the most widely used mouse model for atherosclerosis studies with the defective remnant lipoprotein clearance in these animals promoting the spontaneous development of atherosclerotic lesions within 20 weeks." (PMID 32084149, 2020). "In agreement, inhibition of TRPC5 by isoliquiritigenin was associated with decreased atherosclerosis in ApoE−/− mice." (PMID 32872338, 2020). "TNFα-deficient ApoE−/− mice had decreased plaque size compared with TNFα-sufficient ApoE−/− animals, demonstrating the deleterious role of this cytokine during atherosclerosis development." (PMID 33374145, 2020). "ApoE−/− mice are susceptible to spontaneous development of atherosclerosis, which can be aggravated by keeping them on a high-fat diet." (PMID 33167402, 2020). "In ApoE−/− mice, loss of Jcad was associated with reduced atherosclerosis specifically in areas of disturbed blood flow and with reduced endothelial cell expression of pro-atherogenic cell adhesion molecules." (PMID 31584065, 2020). "CD36 contributes to the process of atherosclerosis because CD36 deficiency prevents plaque development in apoE-/- mice." (PMID 33261070, 2020). "This study investigates the effect of CPH diets in atherosclerosis‐prone apolipoprotein E‐deficient (Apoe−/−) mice." (PMID 32724569, 2020). "Our third aim was to explore the effects of TCEE on the inflammatory response and the progression of atherosclerosis in apolipoprotein E-deficient (ApoE−/−) mice." (PMID 32102326, 2020). "Here, we conducted a pilot study to investigate the impact of mild HHcy on vascular methylating index, atherosclerosis progression and H3K27me3 aortic content in apolipoprotein E-deficient (ApoE−/−) mice." (PMID 32717800, 2020). "Although ApoE is a risk factor for both AD and atherosclerosis, the common mechanism of action remains to be elucidated." (PMID 32069870, 2020). "ApoE is strongly associated with a high risk of atherosclerosis, the leading cause of cardiovascular disease characterized by lipid plaque formation in large vessels." (PMID 33121058, 2020). "Atherosclerosis is lessened in response to myeloid AMPKα1 and AMPKα2 deletion only when on an ApoE-deficient background." (PMID 32978273, 2020). "Our results show that gypenosides can inhibit the development of atherosclerosis in ApoE-deficient mice via regulating changes in mitochondrial apoptosis and energy." (PMID 32685460, 2020). "The quality of PFN1-CD-MNP as a diagnostic agent imaging atherosclerosis was tested using the ApoE-deficient atherosclerotic mouse model." (PMID 32106607, 2020).
atherosclerosis (continued). "This study is aimed at investigating the effects and mechanisms of berberine in protecting the aorta and ameliorating atherosclerosis in apolipoprotein E-deficient (ApoE−/−) mice." (PMID 32566106, 2020). "Genetic deletion of eNOS or over expression of caveolin-1, an endogenous inhibitor of eNOS, has been shown to cause increased leukocyte adhesion and macrophage infiltration, and accelerated atherosclerosis in apolipoprotein E (apoE) deficient mice." (PMID 32536875, 2020). "In comparison to classical apoE−/− models, polG‐deficient mice had increased hyperlipidemia and atherosclerosis." (PMID 32237116, 2020). "The authors also identified perhexiline from a drug screen, as a KLF14 activator, and used this drug to treat ApoE-deficient mice, which have very high total cholesterol levels and develop atherosclerosis." (PMID 32548128, 2020). "In animal models, ApoE deficiency is associated with atherosclerosis, while ApoE deficiency can also result in a reduction in anti-inflammatory M2 macrophages." (PMID 31027190, 2019). "Treatment of ApoE-deficient atherosclerosis-prone mice with LXR agonists significantly reduced atherosclerotic lesion formation, highlighting the atheroprotective effects of LXR pathway induction." (PMID 31191690, 2019). "Atherosclerosis-prone apolipoprotein E-deficient (ApoE-/-) mice exhibit delayed lipoprotein clearance and consequently develop dyslipoproteinemia." (PMID 31861086, 2019). "Our study suggests that ligature-induced periodontitis promotes systemic inflammation, which in turn exacerbates atherosclerosis in ApoE−/− mice possibly by causing aberrant functions of vascular endothelial cells and the activation of macrophages in mice." (PMID 31257363, 2019). "In in vivo studies on mice deficient in apolipoprotein E/adiponectin, there was an increase in IP-10 in plasma, and increased accumulation of T lymphocytes in vessels and atherosclerosis compared to a single apoE deficiency." (PMID 30897855, 2019). "This study generated double-deficient mice for ApoE and IL-12p35 (ApoE-/- IL-12p35-/- mice) and investigated the role of IL-12p35 deficiency in atherosclerosis." (PMID 31093011, 2019). "It has been shown that neutralization of HMGB1 reduces development of atherosclerosis in apolipoprotein E-deficient mice, suggesting significant contribution of decreased HMGB1 by Ipra to the inhibition of vascular remodeling." (PMID 31234839, 2019). "Particularly, apolipoprotein E-deficient (ApoE−/−) mice have been widely used as animal models in the study of hyperlipidemia, atherosclerosis, non-alcoholic fatty liver, and its complications, as well as the physiological function of ApoE." (PMID 31446617, 2019). "For this purpose, 8 week-old male apolipoprotein E-deficient (Apoe−/−) mice were fed with Western diet (WD) for 16 weeks to induce hyperlipidemia and atherosclerosis development." (PMID 31422082, 2019). "For example, high levels of TMAO, ingested directly or from bacterial metabolized choline, increase cardiac inflammation and severity of atherosclerosis in rats and apolipoprotein E-deficient mice." (PMID 31394758, 2019). "In the present work, we offer new insights into the molecular mechanisms underlying the development of atherosclerosis induced by CUMS in ApoE-/- mice." (PMID 30881312, 2019). "Overexpression of antioxidant enzymes in ApoE-deficient mice suppressed B[a]P-accelerated atherosclerosis." (PMID 31439044, 2019). "In apolipoprotein E-deficient mice, a model for atherosclerosis, the hypercholesterolemia leads to early renal dysfunction that can progress into CKD." (PMID 31394758, 2019).
atherosclerosis (continued). "As a model of atherosclerosis, we used hypercholesterolemic ApoE-deficient (apolipoprotein E-deficient) mice, which develop atherosclerotic lesions in the aorta with increasing age." (PMID 30847343, 2019). "We report here the systematic profiling of lncRNAs and mRNAs in an ApoE-deficient (ApoE−/−) mouse model of atherosclerosis." (PMID 31446617, 2019). "Global or VSMC-specific deficiency of LTβR in aged hyperlipidemic ApoE−/− mice demonstrated increased atherosclerotic plaque formation indicating that the VSMC LTβR has the ability to attenuate development of atherosclerosis under some experimental conditions." (PMID 31164888, 2019). "Animal studies had previously indicated that BETi affect plaque parameters; JQ1 attenuated angiotensin II-induced abdominal aortic aneurysm in ApoE (−/−) mice, and apabetalone reduced atherosclerosis in hyperlipidemic ApoE-deficient mice." (PMID 31300040, 2019). "In conclusion, we found that IL-12p35 deficiency alleviated atherosclerosis in ApoE-/- mice; the antiatherosclerotic effect of IL-12p35 deficiency was verified by the regulation of inflammation and was the result of the interaction between IL-12 and IL-35." (PMID 31093011, 2019). "For example, apolipoprotein E-deficient mice are atherosclerosis-prone and have been used to assess the role of microbiota in atherosclerotic processes." (PMID 31182162, 2019). "ApoE is also able to bind to proteoglycan, but in the context of the inflammation associated with atherosclerosis, HDL carries more SAA than apoE." (PMID 31231209, 2019). "We established an atherosclerosis mouse model in ApoE knockout mice, followed by gain- and loss-of-function approaches." (PMID 31757932, 2019). "Atherosclerosis-prone apolipoprotein E-deficient (ApoE−/−) mice which accumulate cholesterol ester-enriched particles in the blood due to poor lipoprotein clearance capacity were used as the atherosclerosis model in vivo." (PMID 31429763, 2019). "We are currently investigating a rodent study by using apolipoprotein E-knockout (apoE KO) mice as our mice model to induce atherosclerosis and identify the role of the LPL inhibitor NDGA on CVD risk and HDL subpopulations." (PMID 31234537, 2019). "Deficient apolipoprotein E (ApoE) expression impairs plasma lipoprotein metabolism and promotes the development of atherosclerosis." (PMID 31695628, 2019). "Knockout IL-1β in atherosclerosis-prone ApoE-deficient mice leads to attenuation of atherosclerosis development." (PMID 31534437, 2019). "The pro-atherosclerotic role of this trio was shown in apoE-deficient mice when joint suppression of these receptors abolished monocytosis and almost completely (up to 90%) diminished atherosclerosis." (PMID 31717832, 2019). "Abnormal function of ApoE is mainly associated with Alzheimer's disease, atherosclerosis, and cardiovascular disease." (PMID 31275318, 2019). "In our hands, in the experimental layout corresponding to a gentle model of atherosclerosis, i.e., in a CD-fed male apoE−/− mice, trehalose caused a 40% reduction of atherosclerotic plaques." (PMID 30925684, 2019). "Accumulating evidence demonstrated that both Th1 and Th17 responses played a pathogenic role in atherosclerosis, while IFN-γ or IL-17 deficiency alone ameliorated atherosclerosis in ApoE-/- mice." (PMID 31093011, 2019). "Studies using ApoE-null mice combined with the deficient chemokine or its receptor have further confirmed their roles in the pathogenesis of atherosclerosis." (PMID 30778913, 2019). "Our aim was to investigate the potential role of a ClC-2 chloride channel activator, lubiprostone, which is reported to have beneficial effects on LGS, in the development of atherosclerosis in apolipoprotein E–deficient (ApoE-/-) mice." (PMID 31206525, 2019).
atherosclerosis (continued). "Our study has also shown that congenital B cell deficiency in μMT−/− ApoE−/− mice decreases atherosclerosis by down-regulating macrophage attractant chemokines, reducing total lesion macrophage numbers, and decreasing inflammation in atherosclerotic lesions." (PMID 31998318, 2019). "There are few studies investigating direct associations between DNA methylation of ABCG1 and APOE and ischemic stroke and atherosclerosis." (PMID 31823830, 2019). "Jacobi and colleagues demonstrated that DDAH1 overexpression ameliorated atherosclerosis in apolipoprotein E (ApoE)-deficient mice." (PMID 31533264, 2019). "Single-cell RNA sequencing was applied to wt (wild type) and ApoE (apolipoprotein E)-deficient aortic adventitia from 12-week-old C57BL/6J mice fed on normal laboratory diet with early stage of atherosclerosis." (PMID 30943771, 2019). "We found that transgenic B2 receptor expression enhanced atherosclerotic plaque formation in the aorta of ApoE–/– mice whereas Bdkrb2 deficiency retarded the development of atherosclerosis." (PMID 30847343, 2019). "Another study in similarity with previous observations reported that APOE-/- mice, which were more susceptible to atherosclerosis, showed some alterations of DNA methylation that favoured the development of atherosclerosis." (PMID 31547615, 2019). "Atherosclerosis, assessed by descending aorta Oil Red O staining, was reduced in ApoE/CD248-deficient mice." (PMID 30847027, 2019). "ApoE-deficient mice exhibit atherosclerosis, while Lrp1 loss from smooth muscle cells enhances vascular cell activation and also leads to atherosclerosis." (PMID 30931303, 2019). "Remarkably, both elevated TMAO plasma levels and the activation of Toll-like receptor (TLR) signaling by MAMPs were shown to accelerate atherogenesis in the apolipoprotein E (Apoe)-deficient mice, which are currently used as an animal model of atherosclerosis." (PMID 31572384, 2019). "ApoE knockout (KO) mice have frequently been used in studies of endothelial dysfunction associated with atherosclerosis and oxidative stress." (PMID 31695628, 2019). "In other mouse models, TLR4 deficiency in atherosclerosis-prone ApoE-deficient mice fed a HFD showed significant reduction of aortic plaque areas, plaque lipid content, macrophage infiltration, and circulating levels of proinflammatory cytokines." (PMID 31582899, 2019). "APOE ε4 is associated with neurovascular dysfunction, has a synergistic effect with atherosclerosis by disrupting cholesterol homeostasis, and also affects vessels via CAA." (PMID 31575706, 2019). "Expression of hedgehog pathway components has been detected in plaques, and inhibition of hedgehog signaling using an antibody that blocks binding of all 3 hedgehog proteins to PTCH1 increased atherosclerosis in Apoe−/− (apolipoprotein E deficient) mice." (PMID 31163988, 2019). "We then tested if the mouse homologs of the peptides provoked immune responses during the disease process in male apoE-/- mice to assess functional relevance to atherosclerosis, the underlying cause of CAD." (PMID 30811493, 2019). "In conclusion, our study showed that AST-120 can preserve the levels of sFlt-1 and suppress the progression of atherosclerosis through the removal of uremic toxins in ApoE-deficient mice with impaired renal function." (PMID 31666542, 2019). "It was also shown that cholesterol-loaded macrophages demonstrated higher APOE gene expression; APOE deficiency in these cells decreased cholesterol efflux and led to atherosclerosis plaques formation." (PMID 30851738, 2019). "The protective roles of KLF2 and KLF4 have been demonstrated in experimental models of atherosclerosis (ApoE-deficient and LDL receptor-deficient mice), where deficiency of KLF2 and KLF4 accelerates the process." (PMID 31354915, 2019).
atherosclerosis (continued). "We conclude that bosentan can prevent endothelial cell death and protect against atherosclerosis in ApoE-deficient mice by upregulating miRNA-21." (PMID 31886257, 2019). "In this study, we generated an animal model of atherosclerosis by raising apolipoprotein E-deficient (ApoE−/−) mice on a high-fat diet and investigated the expression of miRNA-21 and its target PDCD4 during the progression of atherosclerosis in these animals." (PMID 31886257, 2019). "A previous study showed that the omega-6 fatty acid, dihomo-γ-linolenic acid (DGLA), attenuated atherosclerosis in the apolipoprotein E deficient mouse model system." (PMID 31202985, 2019). "The importance of intimal thickening to subclinical atherosclerosis in advancing atherosclerosis has been clearly established in ApoE gene deficient mice fed on a western diet in combination with carotid artery ligation-induced injury." (PMID 31428618, 2019). "This study generated double-deficient mice for ApoE and IL-12p35 (ApoE-/- IL-12p35-/- mice) and investigated the effect of IL-12p35 deficiency on atherosclerosis." (PMID 31093011, 2019). "Our results thus indicated that the protective effect of bosentan against atherosclerosis in ApoE-deficient mice is mediated by miRNA-21." (PMID 31886257, 2019). "Recently, we demonstrated that progerin‐driven vascular smooth muscle cell (VSMC) loss accelerates atherosclerosis leading to premature death in apolipoprotein E‐deficient mice." (PMID 30862662, 2019). "In another study, [(ApoE−/−)/(Nox2y/−)] double knockout mice were used to examine the effects of NOX2-containing NADPH oxidase on the development of atherosclerosis in an atherogenic, ApoE-deficient mice." (PMID 30140678, 2018). "Atherosclerosis was reduced in ApoE-deficient mice treated with PBA, and macrophage apoptosis was decreased." (PMID 29921793, 2018). "In the study we employed atherosclerosis prone apolipoprotein E deficient (ApoE−/−) mice as an animal model which mimics systemic co-morbidities of COPD and accurately reflects the corresponding clinical disease." (PMID 29364178, 2018). "The loss of apoE-mediated atherogenic lipoprotein clearance and reverse cholesterol transport functions contribute to hyperlipidemia-induced atherosclerosis in this murine model." (PMID 30404132, 2018). "Nox1, but not Nox4, seems to be important in atherosclerosis in diabetes, as we demonstrated in Nox1-deficient mice on the atherosclerosis-prone ApoE−/− background made diabetic with streptozotocin." (PMID 29459239, 2018). "Vascular inflammation and atherosclerosis progression are directly linked to EC insulin signaling as demonstrated in ApoE−/− mice." (PMID 28891325, 2018). "In this study, the effects of Rb1 on the development of atherosclerosis were investigated in ApoE-/- deficient mice fed with a western diet." (PMID 30413028, 2018). "Integrins are heterodimeric transmembrane proteins, composed of α and β subunits, that link the extracellular matrix to the cytoskeleton, and global deletion of Itgb3 (encoding integrin β3) exacerbates atherosclerosis in high fat-fed ApoE(−/−) mice." (PMID 29802249, 2018). "The role of primary cilia in the development of atherosclerosis has been revealed in the apolipoprotein-E-deficient mouse model (Apoe−/−) with a high fat and cholesterol diet." (PMID 30486394, 2018). "Because dietary cholesterol in the apoE-/- mouse model generates lesions that are comparable to those observed in humans, numerous studies have employed diet-induced atherosclerosis in apoE-deficient mice." (PMID 30037080, 2018). "In mice, systemic low-dose administration of chloroquine inhibits diet-induced atherosclerosis in ApoE-deficient mice." (PMID 30619297, 2018).